ABCG1 (ATP binding cassette subfamily G member 1)
Diseases named in the same sentence as ABCG1 in open-access papers (continued):
Sharing a sentence is not in itself a finding about the gene and the disease.
prediabetes (2 papers, 2024 to 2025). "Indirect effects of BMI on prediabetes/T2D risk mediated through ABCG1 expression were significant (odds ratio via ABCG1 expression: 1.04 per 1-SD increase in BMI; 95% CI, 1.01–1.07; P = 0.005)." (PMID 38747290, 2024). "Expression of the 3 LXR target genes, ABCG1, ABCA1, and MYLIP, was inversely associated with risk of prediabetes/T2D, with ABCG1 associations (HR, 1.33 per 1-SD decrease; 95% CI, 1.14–1.56; P = 3.63 × 10–4 in the full model) being similar to that of MYLIP." (PMID 38747290, 2024). "Tertile 1 (vs. tertile 3) for ABCG1 expression was associated with incident prediabetes/T2D even in those with normal weight." (PMID 38747290, 2024). "Expression of ABCG1 explained 24% (P = 0.04) of the effect of BMI on prediabetes/T2D risk." (PMID 38747290, 2024). "There appeared to be a graded inverse association between increasing tertiles of ABCG1 and MYLIP expression and the risk of incident prediabetes/T2D in both the Initial and the Replication Study." (PMID 38747290, 2024). "Our data showed that, in addition to coexpressed ABCG1, ABCA1, and MYLIP, expression of NR1H2 (encoding LXRβ) itself was also inversely associated with incident prediabetes/T2D, suggesting, for the first time to our knowledge, that dysregulated LAAMP is a major risk factor for T2D." (PMID 38747290, 2024). "Compared with the full model plus fasting glucose, the addition of ABCG1 expression improved the discrimination and reclassification indexes for prediabetes/T2D, including the C statistic (from 0.763 to 0.784), likelihood ratio test (P = 0.0001), and NRI (0.39; 95% CI, 0.18–0.63)." (PMID 38747290, 2024). "During a median 6-year follow-up, lower expression of 3 highly correlated LXR target genes — ABCG1 and ABCA1 (cholesterol efflux) and MYLIP (cholesterol uptake suppression) — and not other CMTN genes, was significantly associated with higher risk of incident prediabetes/T2D." (PMID 38747290, 2024). "However, within the progression analysis involving individuals transitioning from NGT to prediabetes or T2D, we observed that 2 out of 7 CpG sites—MAN2A1 and ABCG1—exhibited suggestive significance or nominal significance to prediabetes." (PMID 39827095, 2025).
renal carcinoma (2 papers, 2021 to 2025). A carcinoma arising from the epithelium of the renal parenchyma or the renal pelvis. "Further analysis, both on paired and unpaired samples, corroborated the increase in mRNA expression of ABCG1 in renal cancer tissues (n = 539) relative to adjacent tissues (n = 72), with correspondding protein expression levels also elevated." (PMID 40520894, 2025). "There are eight, five, and eight datasets of ABCC3, ABCF1, and ABCG1 for renal cancer, respectively." (PMID 33825659, 2021). "Furthermore, for the first time, the ABCG1 inhibitor Benzamil was introduced in a ccRCC cell line, indicating that ABCG1 may play a crucial role in the etiology and progression of renal cancer." (PMID 40520894, 2025).
Sepsis (2 papers, 2021 to 2024). Sepsis is defined as life-threatening organ dysfunction caused by a dysregulated host response to infection. "Expression of cholesterol efflux transporter Abca1 was unaffected by illness and of Abcg1 increased with sepsis." (PMID 34274000, 2021).
steatosis (2 papers, 2017 to 2019). Increased lipid within the cytoplasm of cells. "In the HC group (rats with steatosis induced by the fatty diet), genes such as ABCG1 and LPL were over-expressed." (PMID 30987167, 2019).
viral infection (2 papers, 2017 to 2024). "RT-qPCR and immunoblotting indicated that HSV-1 decreased both the mRNA and protein levels of ABCA1 and ABCG1, whereas this decrease was restored by RA supplementation, thus suggesting that viral infection inhibited RA synthesis and consequently prevented ABCA1/G1-mediated lipid efflux." (PMID 38989466, 2024).
ZIKV infection (2 papers, 2018 to 2025). "Inhibition of SREBP2 reduces cellular cholesterol levels and suppresses ZIKV infection, whereas ABCG1 deficiency enhances lipid droplet accumulation and promotes ZIKV replication, suggesting that ABCG1 limits intracellular cholesterol availability for viral exploitation." (PMID 40799653, 2025). "Similarly, ZIKV infection increases the expression of both SREBP2 and ATP binding cassette transporter G1 (ABCG1), a cholesterol efflux transporter, in retinal pigment epithelial cells." (PMID 40799653, 2025). "Thus, based on our meta-analysis and the known expression of ABCG1 in RPE cells, we sought to determine its functional role in ocular ZIKV infection." (PMID 30046058, 2018).
acute monocytic leukemia (1 paper, 2013). Acute monoblastic leukemia (AML-M5), is one of the most common subtypes of acute myeloid leukemia (AML) that is either comprised of more than 80% of monoblasts (AML-M5a) or 30-80% monoblasts with (pro)monocytic differentiation (AML-M5b). "Glycation of amino-acid residues in APOA1 alters its binding affinity to ATP-binding cassette sub-family G member 1 (ABCG1) in the human acute monocytic leukemia cell lines (THP-1)." (PMID 24252756, 2013).
alveolar proteinosis (1 paper, 2022). "In alveolar proteinosis, PPARγ regulates the formation of FM by regulating the expression of ABCG1." (PMID 35432274, 2022).
aneurysm (1 paper, 2022). Bulging or ballooning in an area of an artery secondary to arterial wall weakening. "Although the final intracellular cholesterol content might be unaffected by the CEC alterations that we found in AAA patients, ABCG1-CEC reduction could be relevant to aneurysm development or expansion." (PMID 36172376, 2022).
Anxiety (1 paper, 2009). Intense feelings of nervousness, tension, or panic often arise in response to interpersonal stresses. "The performance of ABCG1 BAC Tg mice on tasks measuring anxiety, general locomotor activity and spatial learning and memory were all comparable to those of wild-type animals." (PMID 19239689, 2009). "Both wild-type and ABCG1 transgenic mice performed equivalently on several behavioral tests, including measures of anxiety, as well as on reference and working memory tasks." (PMID 19239689, 2009). "The Elevated Plus Maze, a behavioural task specifically designed to evaluate anxiety, was administered to verify that anxiety levels are not altered in ABCG1 BAC Tg mice." (PMID 19239689, 2009). "ABCG1 BAC Tg mice (n = 11) and wild-type littermates (n = 11; approximately 12 months of age) were next evaluated for anxiety level and general locomotor activity, as both factors can interfere with learning tasks and therefore can drastically affect performance during cognitive assessment." (PMID 19239689, 2009).
Autoimmunity (1 paper, 2024). The occurrence of an immune reaction against the organism's own cells or tissues. "The reduction in CEC was attributed to the ABCG-1-mediated pathway, with an inverse association with disease activity, highlighting the impact of inflammation and autoimmunity on HDL function." (PMID 39456762, 2024).
brain cancer (1 paper, 2016). A primary or metastatic malignant neoplasm affecting the brain. "Collectively, these results demonstrate that ABCG1 is critical for malignant glioma cell survival, and might serve as a future therapeutic target for these deadly brain cancers." (PMID 26981778, 2016).
carotid atherosclerosis (1 paper, 2025). A thickening and loss of elasticity of the walls of carotid arteries that occur with formation of atherosclerotic plaques. "Moreover, KLF11 levels in the aorta were positively correlated with the ABCA1 and ABCG1 levels in normal controls and carotid atherosclerosis patients." (PMID 40397286, 2025). "Correlation analysis revealed that the KLF11 levels in the aorta were positively correlated with the ABCA1 and ABCG1 levels in normal controls and carotid atherosclerosis patients, suggesting that KLF11 regulates ABCA1 and ABCG1 expression." (PMID 40397286, 2025).
colon adenocarcinoma (1 paper, 2023). "ABCG1 protein was detected at lower levels in hypoxic cells surrounding the necrotic centre of spheroids, consistent with observations in mouse colon adenocarcinoma spheroids where expression of ABCG1 and hypoxia-inducible factor 1α are inversely correlated." (PMID 36765727, 2023).
colorectal cancer (1 paper, 2018). A primary or metastatic malignant neoplasm that affects the colon or rectum. "The correlation between ABCG1/2 expression and poor prognosis of patients suffering from colorectal cancer was found with an endpoint of disease-specific survival, although this was not consistent among total nine cohort studies of colorectal cancer available in the meta-analysis." (PMID 30364132, 2018).
coronary artery stenosis (1 paper, 2017). "Recently, even clinical observations have suggested a significant impact of ABCG1 on monocyte function in atherosclerotic processes when decreased ABCG1 messenger RNA (mRNA) levels were found to be inversely correlated with the severity of coronary artery stenosis in CVD patients." (PMID 28383515, 2017).
coronary atherosclerosis (1 paper, 2021). Atherosclerosis of the coronary vasculature. "This suggests that normal EAT is active for reverse cholesterol transport, and hypermethylation of key cholesterol transport genes, including ABCA1 and ABCG1, may play a role in coronary atherosclerosis." (PMID 34837967, 2021).
Down syndrome (1 paper, 2015). "This particular phenotype is observed in Down syndrome people and our results suggest that an increase in one or more genes of the Abcg1-U2af1 region contributes to decreased behavioral flexibility." (PMID 25706610, 2015).
endotoxemia (1 paper, 2024). "Studies have found that, in LPS-induced endotoxemia in mice, LPS inhibit ABCG1 expression and promote the development of inflammation." (PMID 39262873, 2024).
fibrosis (1 paper, 2021). the formation of excess fibrous connective tissue in an organ or tissue in a reparative or reactive process. "The use of myeloid-specific ABCG1 KO mice promoted MWCNT-induced granuloma formation and fibrosis." (PMID 35008476, 2021).
Glucose intolerance (1 paper, 2017). Glucose intolerance (GI) can be defined as dysglycemia that comprises both prediabetes and diabetes. "On the contrary, Abcg1-deficient mice fed a high fat diet were protected from glucose intolerance in comparison to their wild-type littermates." (PMID 28869506, 2017).
Granuloma (1 paper, 2021). A compact, organized collection of mature mononuclear phagocytes, which may be but is not necessarily accompanied by accessory features such as necrosis. "Future studies are required to investigate the molecular mechanism of the efferocytosis process in ABCG1-deficient macrophages and to determine if enhancing ABCG1 expression may reduce apoptosis and ultimately aid in granuloma resolution." (PMID 35008476, 2021). "One limitation in our study is that we have not determined if increasing the expression of ABCG1 in alveolar macrophages may reduce apoptosis and aid in granuloma resolution." (PMID 35008476, 2021).
head and neck cancer (1 paper, 2018). A primary or metastatic malignant neoplasm affecting the head and neck. "The correlation between ABCG1 (P = 0.00715) or ABCG2 (P = 0.0573) expression and poor prognosis of patients suffering from head and neck cancer was found with an endpoint of relapse-free survival." (PMID 30364132, 2018).
metastatic cancer (1 paper, 2018). A carcinoma which has spread from the original site of growth to another anatomic site. "Coincidently, genetic amplification of ABCG1 is found in 10–35% of clinical samples of metastatic cancer cases." (PMID 30364132, 2018). "Genetic amplification of ABCG1 is found in 10–35% of clinical samples of metastatic cancer cases." (PMID 30364132, 2018).
mood disorder (1 paper, 2008). A cognitive disorder a disturbance in which the person's mood is hypothesized to be the main underlying feature. "This notion is supported by the observations that certain polymorphisms in hW, the human homologue of w encoding ABCG1, are linked in males to panic and mood disorders, which are associated with abnormal monoamine functions." (PMID 18167550, 2008).
morbid obesity (1 paper, 2025). An excess of body weight, normally defined as an individual with a body mass index greater than 35 or a body weight greater than one hundred percent of ideal body weight. "In conclusion, the results of this pilot study identify, for the first time, significant associations between genetic dysregulation of hepatic lipid metabolism involving the CROT and ABCG1 genes and the presence of DD symptoms in patients with morbid obesity and implicated MASLD risk." (PMID 40559416, 2025).
Niemann-Pick disease (1 paper, 2016). A group of inherited, severe metabolic disorders in which sphingomyelin accumulates in lysosomes in cells. "The genes contributing to these GO pathways in the DILGOM sample were ATP-binding cassette, sub-family G, member 1 (ABCG1), caveolin 1 (CAV1), Niemann-Pick disease, type C1 (NPC1), and Niemann-Pick disease, type C1, gene-like 1 (NPC1L1), while in the experimental SR study they were ABCA1 and NPC1." (PMID 27102866, 2016).
peripheral artery disease (1 paper, 2021). "We did not analyze ABCA1 and ABCG1 DNA methylation levels in the subgroup of patients with CAD and concomitant carotid artery disease or peripheral artery disease separately, as only three samples from this subgroup were available for DNA methylation analysis." (PMID 34837967, 2021).
prion disease (1 paper, 2014). A transmissible disease that is caused by a protein that is able to induce abnormal folding of normal cellular proteins, leading to characteristic spongiform brain changes, which are associated with neuronal loss without an inflammatory response. "Interestingly, prion disease specifically targets ABCA1, but affects cholesterol efflux not only to the lipid-free apoA-I, which is the preferred substrate of ABCA1, but also to HDL and lipidated apoE, which are preferred substrates for two other transporters, ABCG1 and SR-BI." (PMID 24280226, 2014).
prostate adenocarcinoma (1 paper, 2025). "Furthermore, ABCG1 expression is elevated in prostate adenocarcinoma (PRAD), exhibiting an inverse correlation with overall survival." (PMID 40520894, 2025).
psoriasis (1 paper, 2023). An autoimmune condition characterized by red, well-delineated plaques with silvery scales that are usually on the extensor surfaces and scalp. "It is plausible to question if psoriasis-related inflammatory factors can interact with ABCG1 or ABCA1 to disrupt cholesterol metabolism and epidermal differentiation and exacerbate the inflammatory response." (PMID 37234169, 2023).
renal cell carcinoma (1 paper, 2025). "Recent research suggests ABCG1 may serve as a promising biomarker for renal cell carcinoma." (PMID 40520894, 2025).
situ carcinoma (1 paper, 2020). "We found that the percentage of the Sca-1+Abcg1+subset within the in situ carcinoma tissue reached 2.5%, which was higher than the percentage observed in lung tissue samples from Gprc5a-deficient mice that had not yet developed tumors." (PMID 32157214, 2020).
Tangier disease (1 paper, 2019). "Tangier disease due to ABCA1 deficiency is associated with very low HDL plasma levels and an upregulation of ABCG1 gene expression." (PMID 30611276, 2019).
xanthoma (1 paper, 2022). A non-neoplastic disorder characterized by a localized collection of histiocytes containing lipid. "In our study, the ABCG1-mediated HDL capacity to promote cholesterol efflux (CEC) was lower in patients with xanthoma and inversely correlated with CLC in the entire population of our study." (PMID 35897824, 2022). "Beyond favoring foam cell cholesterol accumulation, a defective ABCG1 HDL-CEC may contribute to xanthoma formation by affecting the inflammatory signaling in macrophages." (PMID 35897824, 2022). "The increased CLC of sera from our patients with xanthoma is not related to changes in plasma lipids but rather to a reduction in the ABCG1 HDL-CEC." (PMID 35897824, 2022). "However, unlike ABCG1 HDL-CEC, the AD-mediated HDL-CEC did not correlate with CLC, ruling out a significant role of this efflux pathway in the higher CLC found in our FH patients with xanthoma." (PMID 35897824, 2022).